KRAS (KRas proto-oncogene, GTPase)
Diseases named in the same sentence as KRAS in open-access papers (continued):
Sharing a sentence is not in itself a finding about the gene and the disease.
tumor (continued). "MCEP2 functions similarly to activated KRAS across different tumor types via its DNA binding access to 5hmC." (PMID 39806421, 2025). "Other predictive markers include mutations in KRAS/NRAS and BRAF V600E, tumor mutational burden, and imaging-based radiomic parameters such as metabolic tumor volume (MTV) and total lesion glycolysis on PET/CT." (PMID 41002551, 2025). "Analysis of all tumors as well as just those initiated with sgInert vectors (which are driven solely by oncogenic KRAS) confirmed that tumor burden, tumor number, and size were all reduced in the aged mice." (PMID 41188600, 2025). "The synthetic lethal interaction between SIAIS562055 and KRAS inhibitors overcame resistance and promoted tumor regression through enhanced ERK inhibition in KRAS-mutant cancers." (PMID 39437162, 2025). "Emerging research highlights the role of the tumor microenvironment in immune evasion and therapeutic resistance, offering opportunities for novel immunotherapy approaches, including KRAS neoantigen vaccines and adoptive T-cell therapy." (PMID 40361439, 2025). "In LUAD, let-7 targets KRAS and MYC, and its downregulation is associated with poor prognosis and increased tumor growth." (PMID 40332376, 2025). "The relationship between KRAS G12 status and tumor molecular subtype (classical and basal-like) emerged as a potential confounding factor in our analysis." (PMID 41061701, 2025). "These tumor-associated macrophages (TAMs) provide cancer cells with trophic support, including TGFβ/SMAD4, enabling KRAS mutation to bypass inhibitory mechanisms in PDAC development (Middle)." (PMID 39806421, 2025). "Molecular markers such as RAS (KRAS/NRAS) mutations, BRAF mutations, HER2 amplification, microsatellite instability (MSI) or mismatch repair (MMR) status, and tumor mutational burden (TMB) have become central to therapy selection and prognosis." (PMID 41228293, 2025). "For example, driver mutations of RAS genes (KRAS type, NRAS, and HRAS) lead to infinite proliferation and enhanced survival of tumor cells." (PMID 40778223, 2025). "The clinicopathological features were similar between KRAS mutant and wildtype patients except for tumor location." (PMID 40279317, 2025). "Growing evidence supports KRAS G12C as a promising tissue-agnostic target, with multiple inhibitors showing activity across tumor types." (PMID 40576713, 2025). "Resultant expression in all tumor cells in combination with the high immunogenicity of the epitope make the KRAS Q61H epitope an attractive target for immunotherapy." (PMID 40165973, 2025). "Further research is required to investigate the role of itaconate in other tumor-associated and tumor-specific antigens (like HER2, KRAS mutations)." (PMID 40521193, 2025). "These processes involve not only canonical oncogenic drivers, such as KRAS, but also dynamic interactions with stromal, immune and vascular compartments that collectively facilitate tumor-cell dissemination and colonization of distant sites." (PMID 41394398, 2025). "Inhibition of HIF1A-As2 suppresses tumor cell proliferation and increases tumor sensitivity to cisplatin treatment, indicating the potential therapeutic value of targeting this lncRNA in KRAS-driven NSCLC." (PMID 39937018, 2025).
tumor (continued). "Consistent with KRAS Q61H being a cancer driver in NSCLC, the hotspot variant was clonal and detected in genomic DNA from a tumor relapse obtained 32 months after surgery of the primary tumor." (PMID 40165973, 2025). "Dual targeting of cancer antigens in KRAS mutated PDAC, MSLN and CEA by computational approaches for elucidation of anti tumor response has been tested." (PMID 40230862, 2025). "The increased glutamine metabolism resulting from SLC25A21 downregulation provides substrates for GTP synthesis, maintaining persistent KRAS activation and promoting tumour progression." (PMID 41154605, 2025). "KRAS protein activation orchestrates intracellular signaling cascades that regulate tumor cell survival and proliferation." (PMID 40141222, 2025). "For 59 CRC tumor samples, LBDA successfully identified KRAS mutations in 37.29% of cases, closely matching results (42.37%) obtained by next-generation sequencing and achieving 88% sensitivity and 100% specificity." (PMID 40422048, 2025). "KRAS mutations significantly remodel the TME, creating conditions that support tumor growth and metastasis." (PMID 40361439, 2025). "KRAS-mutant tumours have been shown to possess lower intracellular NAD+ concentrations, reflecting increased metabolic demand." (PMID 41419662, 2025). "One possibility is given by pulsing DCs with tumor-specific antigens, e.g., using cell lysates, KRAS G12D1–23 peptide, or alpha-enolase." (PMID 40427186, 2025). "In the KRAS G12C-mutated CT26 mouse model, MRTX849 reduced myeloid-derived suppressor cells in the tumor, while increasing the infiltration of M1-type macrophages, dendritic cells, and CD4+ and CD8+ T cells, demonstrating a significant tumor-shrinking effect." (PMID 40303413, 2025). "In summary, KRAS G12C inhibitors not only exert direct anti-tumor effects but also remodel the tumor microenvironment to enhance anti-tumor immunity." (PMID 40303413, 2025). "APC mutation can stabilize both β-catenin and RAS (especially mutant KRAS) proteins, leading to tumor initiation and progression." (PMID 41294868, 2025). "Combining these mouse models with Fluor-HPLC can deepen our understanding of the correlation between KRAS activation states and tumor formation." (PMID 40286847, 2025). "To investigate the clinical relevance of our findings, we performed BH3 profiling on KRAS-mutant NSCLCs (solid metastatic lesions or tumor cells isolated from malignant pleural effusions of patients) after ex vivo exposure to sotorasib or trametinib." (PMID 40316540, 2025). "Among these inhibitors, pyruvate dehydrogenase kinase (PDK) inhibitors have been suggested to suppress tumor metabolism and inhibit tumor growth in KRAS-mutant PDAC, thereby making them one of the promising areas of continued future research." (PMID 40149381, 2025). "Glycolysis inhibition by HK2 KD had similar effects on the tumor immune microenvironment as observed in KRAS inhibition by MRTX1133, including decreased macrophage infiltration and increased CD8+ T cell infiltration and activity." (PMID 39883522, 2025).
tumor (continued). "It exhibited dose-dependent inhibition of KRAS-mediated signal transduction and marked tumor regression in a subset of KRAS G12D-mutant cell-line-derived and patient-derived xenograft models, PDAC in particular." (PMID 40597785, 2025). "siRNA-Based Therapies: Exosomes loaded with siRNAs targeting oncogenes, like KRAS in colorectal cancer, effectively silence tumor-promoting genes." (PMID 40149276, 2025). "In one of the studies, combining trametinib with the new SOS1-KRAS interaction inhibitor BI-3406, which targets the catalytic region of SOS1, makes KRAS-driven tumours more susceptible to MEK inhibition in mice models." (PMID 40483365, 2025). "Currently, there are no validated prognostic biomarkers to predict benefit from mFOLFIRINOX, although KRAS G12 subtype and tumor molecular classification into classical and basal-like subtypes have been used to genotype tumors." (PMID 41061701, 2025). "Studies reporting rapid tumor regression in CRC patients treated with KRAS G12D-specific T cells highlight the potential of KRAS mutations as promising neoantigen targets for immunotherapy." (PMID 40429703, 2025). "Differential effects of oncogenic KRAS and NRAS mutations on proliferation, differentiation, and tumor progression in the colon have been reported in genetically engineered mice." (PMID 40694264, 2025). "DSS-treated APC mut and APC; KRAS mut mice exhibited widespread tumor formation throughout the colon, predominantly in the distal region." (PMID 41285904, 2025). "These exosomes deliver anti-tumor molecules, such as tumor-suppressive miRNAs (e.g., miR-146a) or siRNAs targeting oncogenes like KRAS, effectively downregulating tumor-promoting pathways." (PMID 40149276, 2025). "The prevalence of KRAS and BRAF mutations in proximal tumours from carriers of the rs76011559 minor allele (35% and 19%, respectively) was similar to non-carriers." (PMID 39827162, 2025). "KRAS mutations in GTPase limit the hydrolyzation of GTP to GDP, and sustain the signaling activation, resulting in tumorigenesis and tumor progression." (PMID 40885393, 2025). "Acetylation of RAS at lysine 104 interferes with guanine nucleotide exchange factor‐induced nucleotide exchange, inhibiting the transforming activity of KRAS and thereby reducing cell proliferation, colony formation and tumour burden in mice." (PMID 39778006, 2025). "In addition KRAS controls major signaling pathways involved in tumorigenesis, highlighting the need to understand the clinical impact of mutated KRAS on cancer development and progression, as well as potential differences in prevalence and KRAS-related molecular heterogeneity across tumor types." (PMID 41309533, 2025). "Here, we used the L-iKRAS model to drive NSCLC in mouse lungs; we then inactivated oncogenic KRAS and, as expected, observed tumor regression." (PMID 39782689, 2025). "Our data confirm these previously published results showing that KRAS WT amplifications are a key KRAS driver alteration in multiple tumor types." (PMID 39711431, 2025). "Previous studies have shown KRAS-mutant tumours have lower levels of intracellular NAD+19,20, presumably due to increased metabolic demand." (PMID 41419662, 2025). "For example, the FDA-approved combination of MEK and BRAF inhibitors effectively halts tumor progression in KRAS/BRAF-mutant patients with NSCLC." (PMID 41050683, 2025). "In a syngeneic murine model, β4 subunit knockout in KRAS‐mutant (KRAS‐mt) CRC cells reduced endoluminal tumor engraftment after colonic organoid transplantation to the rectum of C57Bl/6J mice." (PMID 40327521, 2025).
tumor (continued). "Here, we review the influence of oncogenic KRAS on various cell types in the tumor immune microenvironment and summarize the strategies to target the immune microenvironment of KRAS mutant cancer." (PMID 40611261, 2025). "As a final validation, we applied the LBDA technology to detect KRAS gene mutations in tissue samples from 59 CRC patients, including 59 tumor samples and their corresponding peritumoral tissue samples." (PMID 40422048, 2025). "When considering all KRAS mutations, a non-significant trend towards increased responses was observed in patients with KRAS WT tumours (5 of 13, 38%) compared with those with KRAS-mutant tumours (3 of 18, 17%; P = 0.23)." (PMID 41115454, 2025). "Inspection of variants in genes linked to anti‐EGFR therapy (KRAS, BRAF, NRAS, PTEN and PIK3CA) revealed variability across tumours and fractions." (PMID 40302146, 2025). "For instance, KRAS mutations upregulate PD-L1 expression, aiding immune escape, and activate inflammasomes like NLRP3, which further promote a pro-tumor inflammatory milieu." (PMID 40538856, 2025). "Our study shows that synthesizing statin-Cy5.5 conjugates, which are selectively internalized into KRAS-transformed tumor cells via macropinocytosis, can significantly enhance the selectivity of drug delivery." (PMID 40501736, 2025). "Not surprisingly, in both studies, among the genetic regions with losses and gains were KRAS and the usual tumor suppressor genes." (PMID 40227826, 2025). "Other promising immunotherapy strategies, including adoptive T cell transfer targeting mutant KRAS and KRAS-targeted mRNA vaccines, are designed to stimulate tumor-specific T cell responses." (PMID 40429703, 2025). "KRAS is a frequent mutation in NSCLC and is thought to be an “oncogenic driver”, partially explaining the controverse tumor cell reactivity, as LA can inhibit phosphatidylinositol 3‐kinase (PI3K) activated by a KRAS mutation." (PMID 41028965, 2025). "We observed low expression of ATP1A3 and its correlation with increased KRAS signaling and other oncogenic pathways aligns with evidence showing the importance of Na+/K+-ATPase in tumor progression." (PMID 41374320, 2025). "This further explains the involvement of KRAS-mediated Gln in synthesizing Orn in PC cells, in contrast to other tumor cells that rely on Arg to synthesize Orn." (PMID 41281760, 2025). "Consequent MAPK pathway inhibition upon PI3K inhibition has also been demonstrated in PDAC tumor cells but only in the presence of wild-type or inactivated KRAS." (PMID 40227649, 2025). "mRNA vaccines thus provide a new opportunity for the treatment of KRAS-mutant cancer as a promising therapeutic strategy to trigger robust, tumor-specific immune responses." (PMID 41309533, 2025). "Using IPA, we identified a top‐scoring network of 19 upregulated genes in both tumor types stratified into mutant KRAS and WT KRAS samples." (PMID 40013338, 2025). "Synthetic lethality in KRAS-mutant mCRC represents a promising therapeutic strategy by targeting vulnerabilities specific to KRAS-mutant tumor cells while sparing normal cells." (PMID 40361439, 2025). "Among patients with KRAS-mutated NSCLC, the G12C variant comprises 29.4% to 41.5% of cases, making it the dominant KRAS mutation in this tumor type." (PMID 40940900, 2025). "Engineered BEVs are being developed as therapeutic delivery vehicles to deliver anti-cancer agents, including small interfering RNAs (siRNAs) targeting oncogenes such as KRAS, directly to tumor sites." (PMID 40507254, 2025). "Here, we look at changes occurring in the tumor microenvironment upon both activation and inactivation of oncogenic KRAS, including the role of fibroblasts and immune cells in the remodeling process." (PMID 39782689, 2025).
tumor (continued). "NGS can identify actionable mutations, such as EGFR, KRAS, and ALK mutations, that drive tumor growth, enabling more precise and effective treatment decisions." (PMID 39796742, 2025). "KRASG12C mutation is frequently observed across many tumor types, yet KRASG12C is only a fraction of the overall KRAS-mutant patient population." (PMID 39807828, 2025). "At the transcriptomic level, KRAS concentration was higher among the patient group (p = 0.03) and correlated with aggressive tumor features (p = < 0.0001, 0.001, and 0.03, respectively)." (PMID 40913040, 2025). "Oncogenic KRAS significantly reprograms cellular metabolism, enhancing glycolysis, glutaminolysis, and aspartate metabolism to fuel tumor growth and survival." (PMID 39941797, 2025). "The KRAS gene drives metabolic alterations that support tumor growth, while NOXA regulates the balance between cell death and survival." (PMID 40913040, 2025). "The cell death in both scenarios depended on p38, which is also essential for tumor development driven by KRAS or PI3K." (PMID 39805854, 2025). "This tissue-specific divergence underscores the pivotal role of the tumor’s originating microenvironment in shaping KRAS-driven immune checkpoint regulation." (PMID 40303413, 2025). "A high-throughput screen of multicell-type tumor spheroids was designed to identify active combinations of targeted small molecules and KRAS pathway inhibitors." (PMID 40960119, 2025). "In the next section, we review these regulatory mechanisms and their variation across tumor types before discussing currently approved and ongoing investigations of KRAS-targeted therapeutic strategies." (PMID 41309533, 2025). "In patients with KRAS, NRAS or BRAF mutation and the moderate to strong expression of all three of these proteins in the tumor microenvironment, the number of metastatic lymph nodes was higher than in other patients." (PMID 39857068, 2025). "The combination of BD-9136 and gemcitabine also suppressed the in vitro growth of a mouse oncogenic KRAS (KPC) PDAC cell line as well as pancreatic orthotopic tumor growth." (PMID 39774001, 2025). "The complexity of KRAS mutation patterns in CRC is further underscored by studies investigating their correlations with patient age and tumor location." (PMID 40949797, 2025). "SPP1_TAMs were significantly enriched in pathways such as KRAS signaling up, Coagulation, and Hedgehog signaling, suggesting a potential role in promoting tumor vascularization." (PMID 41246334, 2025). "MEDI3622 has shown remarkable efficacy in inhibiting tumour growth in CRC PDX models, including those with KRAS mutations." (PMID 40427200, 2025). "Oncogenic KRAS promotes an immunosuppressive tumor microenvironment (TME) in PDAC, whereas inhibition of RAS signaling can partially reverse this phenotype." (PMID 41471277, 2025). "Triple therapy with Remodelin, cetuximab, and 5-Fluorouracil enhanced tumor regression in xenograft mouse models of CRC with wild-type KRAS, NRAS and BRAF." (PMID 39905540, 2025). "The strategy followed for KRAS.SOS1 ternary complex can be extended to other RAS proteins involved in tumor progression, such as targeting the HRAS.SOS1 ternary complex with known 3-dimensional structure." (PMID 40244134, 2025). "Glecirasib monotherapy leads to tumor regression in KRAS G12C–mutant animal models and shows synergistic effects with cetuximab or JAB-3312 (sitneprotafib)." (PMID 40304209, 2025).